SOX2 (SRY-box transcription factor 2)
Diseases named in the same sentence as SOX2 in open-access papers (continued):
Sharing a sentence is not in itself a finding about the gene and the disease.
breast cancer (continued). "Via IF assay, OCT4 and SOX2 expressions increased in breast cancer tissues compared with paired-adjacent non-tumor tissues." (PMID 35402219, 2022). "By suppressing FOXO1 degradation and increasing SOX2 transcription, TRIB3 can help breast cancer." (PMID 36245981, 2022). "Similarly in breast cancer, the NF-κB pathway regulates the expression of OCT4, SOX2, and NANOG via upregulation of components of the NF-κB signaling pathway, including NIK 56,57." (PMID 36118530, 2022). "On the other hand, high SOX2 and AGR2 expression with high serum level of serum AGR2 may predict a subset of breast cancer patients that are less likely to show adequate tumor growth control or recurrence following tamoxifen therapy." (PMID 34567804, 2021). "In this work, we show the effects of the SOX2-iPep in cancer cells and a negative trend between SOX2 mRNA levels and overall survival in breast cancer patients." (PMID 34502261, 2021). "Hence, we propose that a dual reporter including one of the pluripotency markers (phOCT4-EGFP/NANOG-GFP/SORE6-GFP/SOX2 SRR2-pGreen fire) and ALDH1A1-DsRed2 can efficiently mark all the heterogeneous CSCs, at least in breast cancer." (PMID 34150761, 2021). "Several studies focusing on breast cancer (BC) found that the expression of Nodal strictly correlates with the expression of stem cell markers such as CD44 and CD133 and embryonic TFs such as Sox2, Oct4, and Nanog." (PMID 34360603, 2021). "The expression of IL20RA was positively correlated with that of SOX2 in tumors and noncancerous tissues of both breast cancer and colorectal cancer patients." (PMID 33456560, 2021). "The relation between Sox2 and AGR2 expression and breast cancer has been broadly studied." (PMID 34567804, 2021). "Studies have identified CD44+CD24− in breast cancer; CD44+CD24+EpCAM+ in pancreatic or ovarian cancer; and a high expression of neuron stem markers, such as CD133, CD44, and Nestin, and transcript factors, such as SOX2 and OCT4, in GBM." (PMID 34069945, 2021). "Furthermore, ginsenoside Rg3 reduces HIF-1α expression to down-regulate SOX-2 and Bmi-1 expression levels, leading to decreased stemness and CSC features in breast cancer." (PMID 34769099, 2021). "SOX2 is not expressed in most normal adult tissues but is expressed in ∼43% of basal-like breast cancers." (PMID 34988459, 2021). "Our results in this study show that tangeretin inhibits the Stat3/Sox2 signaling pathway and induces CSC death, indicating that tangeretin may be a potential natural compound targeting breast cancer." (PMID 32503228, 2020). "Our results in this study showed that betavulgarin inhibited the Stat3/Sox2 signaling pathway and induced BCSC death, indicating that betavulgarin might be a potential natural compound that targets breast cancer and BCSCs." (PMID 32630026, 2020). "In CSCs, SOX2-mediated drug resistance was acquired through activation of EMT pathway in CRC, HNSCC, PDAC, and breast cancers." (PMID 30517668, 2020). "This supports our hypothesis that SOX2 directly transactivates DNMT1 expression and thereby alters the methylation landscape and feedback inhibits FOXO3a expression in breast cancer." (PMID 31296961, 2020). "We should mention that OCT4, NANOG, and SOX2 could also explain the effect of ZFHX3 on BCSC features as they are known stem cell factors, and their expression was also upregulated by ZFHX3 in breast cancer cells." (PMID 33217982, 2020). "Functional studies revealed that overexpression of HOTTIP markedly promoted cell clonogenicity, increased the expression of the stem cell markers, OCT4 and SOX2, and decreased the expression of the differentiation markers, CK14 and CK18, in breast cancer cells." (PMID 32307830, 2020). "This study did not demonstrate any significant Sox2/HER2 associations, as reported in human breast cancer." (PMID 33553286, 2020).
breast cancer (continued). "A likely explanation is that Sox2 facilitates the G1/S transition of the cell cycle and up-regulates the CCND1 (cyclin D1) gene, as demonstrated in the luminal MCF-7 and triple-negative MDA-MB-231 breast cancer cell lines." (PMID 33553286, 2020). "Moreover, ICAM3, CCL16, PDE3A, PRTN3, TRAF6, BCAR1, IL-1α, IL-1β, NFκB1, SOX2 and OCT4 decreases the protein expression as indicated by immunofluorescence staining in the ibuprofen-treated MDA-MB-231 breast cancer cells versus the control." (PMID 32528119, 2020). "First, we evaluated the ALDH activity, the expression of BCSC genes (Nanog, Sox2 and Oct4), multiresistance pumps (ABCG2, ABCC1 and ABCB1) and the BCSC frequency (CD44+CD24+CD49+EPCAM+) in three human breast cancer cell lines." (PMID 33184339, 2020). "The observation that Sox2 or VEGF alone failed to induce the endothelium generation of breast cancer cells prompted us to determine the role of VEGF signaling in this process." (PMID 32541667, 2020). "Accordingly, treatment of mammospheres from the luminal-B (but not the luminal-A) breast cancer patient with iadademstat significantly reduced the expression of SOX2, likely indicating a selective targeting of SOX2-driven CSC." (PMID 32191225, 2020). "Unfortunately, a better understanding of Sox2 biology in mammary carcinomas is unlikely to have therapeutic implications in the near future." (PMID 33553286, 2020). "Furthermore, p75NTR regulates the expression of pluripotency transcription factors, including Sox2, Nanog, and MYC, promotes CSCs self-renewal in breast cancer, and facilitates symmetric divisions in slow-proliferating or quiescent CSCs." (PMID 31812953, 2019). "Our results revealed that the simultaneous existence of YB-1 and the other four (SOX2, POU3F2, OCT-4, and OLIG1) or five (SOX2, SALL2, OCT-4, POU3F2, and Bmi-1) transcription factors reverted YB-1-deleted melanoma stem cells or breast cancer stem cells, respectively, into cancer stem cells." (PMID 31375149, 2019). "Although a recent study showed that knockdown of HIF-1α decreased hypoxia-mediated SOX2 upregulation and prostate cancer cell invasion, the molecular link between SOX2 and HIF-1α in breast cancer cells under hypoxic conditions remains unclear." (PMID 31462898, 2019). "It is therefore interesting to investigate whether Rac1 and HIF-1α work as downstream effectors of SOX2 and NEDD9 in hypoxic breast cancer cells." (PMID 31462898, 2019). "The findings of this study revealed decreased expression of β-catenin, Oct4, Sox2, Snail1, and the subsequent increased expression of E-cadherin by rBmK AGAP both in vitro and in vivo which to reduce breast cancer cell stemness and epithelial-mesenchymal transition." (PMID 30740360, 2019). "We proposed that SOX2 rather than other pluripotency factors plays a vital role in supporting the breast cancer stemness in breast cancer with high TRIB3 expression." (PMID 31844113, 2019). "Interestingly, latency competent breast cancer cells (LCBCC, cancer cells that can reseed organs with latent metastasis) have been found to maintain a stem cell-like state and express Sox2 and Sox9 transcription factors." (PMID 31394796, 2019). "Our study is the first to reveal that SOX2 and NEDD9 may function as novel upstream regulators of Rac1/HIF-1α in hypoxic breast cancer cells." (PMID 31462898, 2019). "To understand whether the downregulation of TLR5 could promote breast cancer metastasis and invasion, we detected EMT markers and its signal pathway, TRAF6 and SOX2." (PMID 31852883, 2019). "SOX2 and SOX10 are often present in breast cancer, although their role is poorly understood yet." (PMID 29739401, 2018). "Breast cancer stem cell (BCSC)-specific markers were highly reduced upon VDAC1 silencing in tumours established from the TNBC MDA-MB-231cell line, including ALDH1, CD133, EPCAM, SOX2 and KLF4." (PMID 30544833, 2018).
breast cancer (continued). "To understand potential links between aging and breast cancer stemness, we employed the GenAge Human Genes list to screen for genes that are correlated with core stemness factor OCT4, SOX2, NANOG, and KLF4 in a cohort of breast cancer cell lines collected from the TCGA database." (PMID 30038266, 2018). "For example, in a study of breast cancer patients, SOX2 was strongly detected by immunohistochemistry in the nucleus of breast carcinoma cells compared to weak or no SOX2 staining in normal, non-tumorigenic mammary epithelial issue." (PMID 28388544, 2017). "The breast cancer cells ZR-7530 and MDA-MB-231 express high levels of SOX2 protein." (PMID 28288641, 2017). "Spearman’s rank order correlation coefficients of relative gene expression values (fold change) for AXIN2, DKK1, and SOX2 versus IC50 value of the WNT inhibitors LGK974 and IWP-2 in MCF-7 parental and endocrine therapy-resistant breast cancer cell lines (n = 14)." (PMID 28929082, 2017). "And expression of SOX2 and SOX2OT were concordant in ESCC and breast cancer." (PMID 27974698, 2017). "In breast cancer stem cells, HOTAIR has been shown to contribute to the proliferation, migration, colony formation, and self-renewal capacities through transcriptionally inhibiting miR-34a of breast CSCs, leading to upregulation of Sox2." (PMID 29228709, 2017). "SOX2 and PPRAG have already been reported to take part in the activation of breast cancer." (PMID 28607444, 2017). "To validate our findings in vivo, we tested whether high VEGFA alone or together with high SOX2, SNAI2 and decreased miR-452 expression might identify prognostic subsets of primary human breast cancers." (PMID 28504716, 2017). "We recently showed that SOX2 was expressed at higher levels in estrogen receptor-positive (ER+) breast tumor tissue samples from The Cancer Genome Atlas (TCGA) data set and also in tamoxifen-resistant MCF-7 breast cancer sub-lines." (PMID 28929082, 2017). "As for the minimal change in expression of SOX2, OCT4, and NANOG following therapeutic treatment in the MCF7 cells, this may be due to MCF7 being a luminal breast cancer subtype." (PMID 28871147, 2017). "Normal positive staining patterns for OCT4 (brown), NANOG (purple), SOX2 (brown), c-Myc (brown), and KLF4 (purple) were demonstrated on human seminoma, normal skin, breast cancer, and prostate tissues, respectively." (PMID 29404335, 2017). "Here we show that nuclear protein 1 (Nupr1), a protein independent of Sox2, is downregulated in TRCs of melanoma, ovarian cancer and breast cancer cultured in soft fibrin matrices." (PMID 27089143, 2016). "Our current study reveals that Nupr1, independent of Sox2, is low in three types of carcinoma TRCs (melanoma, ovarian cancer and breast cancer) and is a negative regulator of TRC growth." (PMID 27089143, 2016). "In human cancers, SOX2OT is co-upregulated with SOX2 and OCT4 in esophageal squamous cell carcinoma and was also suggested to play key roles in the induction and/or maintenance of SOX2 expression in breast cancer." (PMID 27833660, 2016). "We then showed that two commonly used human breast cancer cell lines (MCF7 and MCF10Ca1h) express detectable levels of SOX2 and OCT4 mRNA in bulk culture, though the level was two to four orders of magnitude lower than is seen in the human teratocarcinoma line NT2." (PMID 25497455, 2015). "Ectopic expression of G9a also increased Sox2 protein levels in another ER(+) breast cancer cell line, ZR-75-1, whereas it did not affect Sox2 expression in MDA-MB-231 cells, an ER(-) breast cancer cell line, or in glioblastoma cell lines." (PMID 26492085, 2015). "We found it interesting that the effect of G9a overexpression on the Sox2 protein was only observed in ER(+) breast cancer cell lines such as MCF7 and ZR-75-1, but not in ER(-) MDA-MB-231 cells." (PMID 26492085, 2015).
breast cancer (continued). "To determine whether such low levels of SOX2 and OCT4 were sufficient to drive reporter expression, we transduced the MCF10Ca1h breast cancer cell line with the SORE6 reporter." (PMID 25497455, 2015). "We chose the MCF7 breast cancer cells as a model cell line to study the temporal dynamics of the incorporation of DNAme, as these cells express high levels of SOX2, and the promoter does not contain methylated CpG dinucleotides." (PMID 25684141, 2015). "Unlike estrogen receptor-positive breast cancer cells, Sox2 is not a major contributor to the reporter responsiveness." (PMID 25868977, 2015). "Analysis of the genome-wide RNA transcript profiles from the Cancer Genome Atlas (breast invasive carcinoma gene expression) by RNA Seq data set in 1106 samples of breast cancer tissues revealed the concordant expression of SOX2OT and SOX2 in this somatic cancer." (PMID 26136768, 2015). "In the breast, SOX2 expression has not been reported in healthy tissues but is detectable across different breast carcinoma (BC) subtypes and particularly prominent also in certain BC-derived metastases." (PMID 26498353, 2015). "Although transcription factors are not classical drug targets, approaches to SOX2-targeted therapy are already being addressed in breast cancer." (PMID 25300947, 2014). "The induction of SOX2 by ectopic expression of SOX2OT establishes a possible signaling pathway but does not prove that this pathway is important in human breast cancer." (PMID 25006803, 2014). "Since SOX2 and CDX2 have been shown to repress each other's expression, we next asked whether ratio between two genes has an impact on breast cancer outcome." (PMID 23982413, 2013). "SOX2 plus EGFR had similar prognostic impact on ER-negative but not specific subtypes of breast cancer (data not shown)." (PMID 23982413, 2013). "SOX2 was also reported to synergistically interacted with β-catenin, the downstream molecule of the WNT signal pathway, to regulate the transcription of a target gene to promote cell proliferation and tumorigenesis of human breast cancer." (PMID 22615765, 2012). "SOX2 expression was detected across different breast cancer subtypes and did not correlate with tumor grading." (PMID 21276239, 2011). "It is also found that CHD4 regulates SRY-box 2 (SOX2: regulator of stem cell pluripotency and has a role in the function of cancer stem cells, CSCs) transcription through TRPS1 (GATA-type transcription factor that promotes angiogenesis) in luminal breast cancer." (PMID 40004553, 2025). "Thus, for example, CSC from breast cancer express CD44, CD49f, CD133, ALDH1, and Sox2; prostate CSC are known to express CD133, CD44, integrin α2β1, CD49f, ALDH1, EZH2, and SOX2; while colon CSC express CD133, CD44, CD49f, and ALDH1, showing an overlap in the CD133, CD44, CD49f, and ALDH1 markers." (PMID 39859345, 2025). "In MDA-MB-231 cells, GATAD2B knockdown significantly reduced expression of cancer stem-like cells factors OCT4, SOX2, c-Myc and NANOG, at both protein and mRNA level, further implicating the role of GATAD2B in maintaining cancer stem-like cells phenotype in breast cancer cells." (PMID 40136647, 2025). "The exact mechanism behind Shh maintaining the CSC self-renewal capabilities is unknown; however, studies performed on thyroid cancer, embryonal RMS, and breast cancer revealed that increased Shh and SMO signalling lead to increased expression of SOX2, NANOG, OCT3/4, and KLF4 transcription factors." (PMID 38920995, 2024). "Notably, WT-RAC1 increases SOX2 at a much-attenuated level compared to CA-RAC1, consistent with the conclusion from MDA-MB-231 cells that the activation is required for RAC1 to increase breast cancer cell stemness." (PMID 39463384, 2024).
breast cancer (continued). "The silencing of STAT3 by shRNA in HER2 overexpressing breast cancer cells resulted in a reduction in CD44-positive cells and the downregulation of the expression of stem cell markers, such as Octamer-binding transcription factor (OCT-4) and SRY (sex determining region Y)-box 2 (SOX-2)." (PMID 38067351, 2023). "Sox2-reactive breast cancer is more tumorigenic than nonreactive breast cancer." (PMID 35992805, 2022). "SOX2 has been illustrated to increase cellular proliferation, colony formation, and metastasis by promoting WNT/β-catenin signaling and epithelial-mesenchymal transition (EMT) and downregulating AMP-activated protein kinase/mTOR signaling in breast cancer cells." (PMID 35402219, 2022). "We found that p97 was consistently at a higher level in the CD44+/CD24−, ALDH+, or PKH26+ CSC populations than the respective non-CSC populations in human breast cancer tissues and cancer cell lines and p97 expression also positively correlated with that of SOX2, another CSC marker." (PMID 33731668, 2021). "Conversely, SOX2 or MYC mRNAs were significantly downregulated in cells expressing TrkA-K538N, nearly to the levels found in the vector controls, suggesting that TrkA kinase activity is essential for inducing STAT3 target gene transcription in breast cancer cells." (PMID 34066153, 2021). "Notably, SOX2 deregulation has been demonstrated in 43% of basal-like breast carcinomas, which are triple-negative malignancies lacking the hormonal receptors and HER2." (PMID 34502261, 2021). "To determine whether IL20RA plays a role in breast carcinomas and to further investigate its function in stemness regulation, we examined the expression of IL20RA and SOX2 using tissue microarrays containing human normal/para-carcinoma breast tissues and breast tumors." (PMID 33456560, 2021). "Third, because SOX2 confers sensitivity to LSD1 inhibition, we characterized the SOX2 expression pattern using the PAM50 classifier and the integrative clustering of transcriptional data available from the Molecular Taxonomy of Breast Cancer International consortium (METABRIC)." (PMID 32191225, 2020). "Therefore, we hypothesized that SOX2 directly transactivates DNMT1 expression and thereby alters the methylation landscape and inhibits FOXO3a expression in breast cancer." (PMID 31296961, 2020). "Our data indicated that Sox2 alone could not induce the generation of breast cancer cells to EC in vitro, but successfully induced endothelium generation with VEGF." (PMID 32541667, 2020). "Importantly, we observed a significant inverse correlation between FOXO3a and FOXM1/SOX2/DNMT1 expression levels, and a significant positive correlation between FOXM1, SOX2, and DNMT1 in the breast cancer tissue set, which was consistent with our finding in vitro and in animal model." (PMID 31296961, 2020). "Interestingly, CXCR2 could be also a potential cancer stem-like cell marker, as a costaining of some breast cancer cells with NANOG and SOX2 has been reported and also that CXCR1/2 inhibition decreases mammosphere formation." (PMID 32727083, 2020). "Klf4 with Oct4 and Sox2 induces the expression of Lefty1 and Nanog, KLF4 is also a prognostic predictor of colon cancer and head neck squamous cell carcinoma, and is also detected in leukemia, myeloma, testis cancer, early stage breast cancer, nasopharyngeal cancer, and oral cancer." (PMID 32493501, 2020). "Interestingly, while breast cancer sphere-forming cells showed high SOX2 expression, NANOG and OCT4 were not expressed in these cells, suggesting the presence of heterogeneous CSC populations." (PMID 31137841, 2019).